IRF7 (interferon regulatory factor 7)
Diseases named in the same sentence as IRF7 in open-access papers (continued):
Sharing a sentence is not in itself a finding about the gene and the disease.
viral infection (continued). "In addition, chicken IRF7 may regulate genes involved in the cell structural integrity or cellular assembly such as cell adhesion, ECM organization, and adherens junctions which have a wide range of functions in the host response to viral infection." (PMID 30356848, 2018). "Thus, the sequential involvement of IRF3 and IRF7 in the early and later phase of TNF production allows us to postulate that, if the early phase production of TNF and type I IFN is sufficient to block viral infection, then the later phase production of both cytokines will be coordinately curtailed." (PMID 18617992, 2008). "By limiting the transcription of IRF7, FOXO3 thus prevents leakiness in IFN signaling in the absence of viral infection." (PMID 39995872, 2025). "Honda and Taniguchi reported that the homodimer of IRF7 or the heterodimer of IRF7/IRF3, rather than the homodimer of IRF3, is more important for the production of IFN-I under viral infection." (PMID 37638030, 2023). "IRF7 is the antagonistic target of PRRSV and plays an important role in the innate immune response against virus infection, which can regulate ISGs expression in the absence of IFN signaling." (PMID 35154273, 2022). "ISG15 is one of the most highly induced ISGs in viral infections, and it has also been found to be directly induced by IRF3/IRF7, independent of IFNs (46, –, 48)." (PMID 33785572, 2021). "In contrast, IRF7 was virtually absent, but strongly induced by IFN treatment and virus infection, underscoring its role as a positive feedback mechanism of the antiviral system." (PMID 34685580, 2021). "IRF1, IRF5, and IRF7 can induce the expression of IFIT and IFITM proteins in the absence of viral infections." (PMID 32499867, 2020). "Most importantly, even without virus infection, IFN-β alone induced RIG-I, and siRNA against IRF7 did not inhibit RIG-I induction by IFN-β." (PMID 32235406, 2020). "MEFs lacking both 4E-BP1 and 4E-BP2 are extremely resistant to viral infections due to increased type-I IFN production and high Irf-7 mRNA translation." (PMID 25531441, 2014). "IRF-7 mRNA was detected in primary hepatocytes (PHH) and HuS-E/2 cells, but not HuH-7 cells, one of hepatocellular carcinoma derived cell lines, without virus infection." (PMID 24587086, 2014). "IRF7 is largely responsible for IFN production in response to viral infection, as evidenced by the abrogation of IFN production in Irf7 −/− mice, but not in Irf3 −/− mice." (PMID 23555825, 2013). "Although IRF3 has been shown to mediate TNF induction under various circumstances, such as lipopolysaccharide stimulation or certain viral infections, the collaboration between IRF3 and IRF7 resulting in sustained TNF induction has not been recognized before." (PMID 18617992, 2008). "In contrast, IRF7 and RSAD2 were not induced by viral infection of ΔIRF7 cells." (PMID 34411201, 2021). "Importantly, in the absence of the viral infection in early-life, exposure to CRE alone did not induce experimental asthma in IRF7-/- mice." (PMID 32658914, 2020). "IRF3, IRF7, and IFNB1, which are upregulated naturally in response to viral infection, could not stimulate an immune response due to the activation of the P viral protein." (PMID 27872612, 2016). "The decrease in expression of pGL3-PURA in the presence of overexpressed IRF-3, IRF-5, and IRF-7 and the specific binding of IRF-3 to sequence near TSS II led us to investigate whether or not viral infection could affect PURA transcription." (PMID 21062477, 2010).
COVID-19 (87 papers, 2020 to 2026). A disease caused by infection with severe acute respiratory syndrome coronavirus 2. "In previous studies of familial clusters of patients with severe COVID-19 across Sweden, we identified two brothers with a homozygous LoF IRF7 variant, as well as two brothers with a novel X-linked TLR7 LoF variant." (PMID 38231281, 2024). "Levy and collaborators reported the safety of a single subcutaneous injection of Peg-IFN-α2a in two patients with inborn errors of the TLR-3 and IRF-7, affecting the production of type I IFNs and predisposing to severe COVID-19." (PMID 38288121, 2023). "With the analysis of the most frequent comorbidities in COVID-19, the authors found that the hub protein IRF7 is upregulated in COVID-19 patients, which is associated with the pathogenesis of diabetes mellitus and lung cancer." (PMID 37638030, 2023). "Examination of the genetic patterns in COVID-19 positive patients revealed a link between mutations in the IRF7 gene and COVID-19 mortality rates in African Americans, especially pronounced in elderly cohorts." (PMID 38022551, 2023). "Genetic mutations TLR3, TLR7, and IRF7-dependent and neutralizing autoantibodies inhibited type I interferon signaling in COVID-19 patients who had severe disease." (PMID 36726976, 2022). "A recent study identified the loss-of-function mutation at the loci of TLR3 and IRF7 in severe patients with influenza and COVID-19, resulting in preventing type 1 IFN production, thus emphasizing the significance of type 1 IFN in controlling virus production." (PMID 33362771, 2020). "The IRF7 c.887-2 A>C variant has been identified in critical/severe COVID-19 cases, suggesting that this specific variant may be associated with increased disease severity." (PMID 41012626, 2025). "Additionally, type I interferon immunity deregulation due to IRF7 deficiency was suggested as a possible molecular mechanism of severe and life-threatening COVID-19." (PMID 37795240, 2023). "RTEL1 is linked to pulmonary fibrosis, TRIM34 plays a role in restricting HIV-1 infection, PPP2R2A is a potential therapeutic target, and IRF7 shows high expression in certain COVID-19 patients, underlining the diverse implications of these genes in the context of SARS-CoV-2 infection." (PMID 38681774, 2023). "In another work, TLR-3, IRF3, and IRF7 variants were detected in patients with severe COVID-19." (PMID 35062298, 2022). "Furthermore, the IRF7 mutation causing loss of function was reported to be associated with severe pneumonia progression in COVID-19." (PMID 35625619, 2022). "It has been found that about 3.5% of COVID-19 patients had known autosomal-recessive (AR) deficiencies [interferon regulatory factor 7 (IRF7) and IFNAR1] and autosomal-dominant deficiencies (AD) [toll-like receptor 3 (TLR3), UNC93B1, TICAM1, TBK1, IRF3, IRF7, IFNAR1, and IFNAR2]." (PMID 34335535, 2021). "It has been reported that inborn errors of TLR3 and IRF7 dependent type-I IFN immunity may be associated with COVID-19 symptoms and outcomes." (PMID 33780352, 2021). "Correlation plots between TMPRSS2 and commonly upregulated genes were representively shown for OAS1, STAT1 and IRF7 from COVID-19 vs. healthy PBMNCs." (PMID 40055791, 2025). "We found that IRF7 is significantly up-regulated in both AD and COVID-19 and, together with STAT genes (such as STAT2), are located in the core of the signaling transduction module." (PMID 38257800, 2024). "DCs from healthy donors were stimulated with opsonized SARS-CoV-2 with serum from either mild or severe COVID-19 patients and induction of IFNβ, ISGs, such as IRF7, and IL-6 was measured." (PMID 38418557, 2024). "Lastly, we observed the positive correlation between ACE2 and IRF7 expressions both in the frontal cortex of COVID-19 patients and in the hippocampal formation (HF) of SARS-CoV-2-infected AD patients." (PMID 38257800, 2024).
COVID-19 (continued). "Serum from both COVID-19 mild and severe patients suppressed IRF7 and IL-6 induction, which was restored by CD32/FcγRII inhibition." (PMID 38418557, 2024). "Specifically, the IRF7 (+) regulon was activated in severe COVID-19, whereas FOS (+) and JUNB (+) regulons were activated in healthy neutrophils." (PMID 38612651, 2024). "The analysis identified enrichment for rare variants in 13 gene loci involved in TLR3- and IRF7-dependent immunity, with experimental validation including evidence for a role for autosomal recessive AR deficiencies of IRF7 and IFNAR1 in severe COVID-19." (PMID 38549844, 2024). "Recent investigations report an elevated expression of genes encoding IRF1, IRF5, IRF7, JAK2, and PML in severe COVID-19 patients." (PMID 38022551, 2023). "Autosomal-recessive and autosomal-dominant deficiencies of IRF7 are involved in the TLR3- and IRF7-dependent induction and amplification of IFN-I, and TLR7 together with IRF7 combat COVID-19 by the large amounts of IFN-I produced by pDCs." (PMID 37638030, 2023). "We found that the expression pattern of IRF7 in both PBMCs and monocytes increased with the severity of COVID-19." (PMID 37310504, 2023). "Lastly, the four rare variants (two in the IRF7 gene, one in SLC6A20 gene and one in DDX58 gene) segregating in a patient with a severe phenotype of COVID-19 (family n°6), were all evaluated as “tolerated” with a CADD score <25." (PMID 36228008, 2022). "We observed that TLR7, together with MAVS, TLR9, IRF7, was downregulated in pDCs in the COVID-19 groups but more so in the groups with severe disease." (PMID 36439166, 2022). "Whole exome/genome sequencing based study in 659 cases with severe COVID-19 identified variants in 13 loci, predominantly affecting TLR3 and IRF7 dependent activation of type I IFNs." (PMID 35601440, 2022). "The results of Cox analysis revealed that the RACGAP1, TCF7L2, IRF7, DMD, and JUN were significantly associated with the development of COVID-19/BRCA (p < 0.05)." (PMID 36060002, 2022). "In 23 people from the 659 patients with severe COVID-19 autosomal recessive (IRF7, IFNAR1) and autosomal dominant (TLR3, UNC93B1, TICAM1, TBK1, IRF7, IRF3, IFNAR1, IFNAR2) deficiencies were found." (PMID 36142877, 2022). "Recent studies show that methylation levels of IRF7 correlate with COVID-19 severity, which is also consistent with the conclusions in the data source literature." (PMID 36212830, 2022). "FBA was also able to up-regulate the expression of genes involved in the TLR signaling pathway, such as CHUK, an inhibitor of Nf-kB, TRAF6, a mediator of the inflammatory response and Irf7, which is correlated with COVID-19 gastrointestinal symptoms." (PMID 35164139, 2022). "Activated Myc represses IRF7 and a significantly lower abundance of IRF7 was found in patients with COVID-19." (PMID 35663963, 2022). "In particular, autosomal-recessive deficiencies in IRF7 and IFNAR1 and autosomal-dominant deficiencies in TLR3, TBK1, IRF3, IRF7, IFNAR1 and IFNAR2 genes have been found in a small percentage of patients with severe influenza and COVID-19." (PMID 35846766, 2022). "Consistent with this, rare pathogenic variants in TLR7 and eight candidate loci, including, TLR3, IRF3, and IRF7 governing type I IFN response have been identified in patients with critical COVID-19." (PMID 36143338, 2022). "Recent research in adult SARS-CoV-2 cases has identified associations between severe COVID-19 and several rare genetic variants in genes implicated in TLR3-, TLR7-, and IRF7-dependent IFN type I immunity, including heterozygous variants in the gene TBK14–7." (PMID 34210994, 2021). "Furthermore, in mouse models, the early phase of SARS-CoV-2 infection causes an upregulation of the Tlr7, Irf7 and IFN-I pathways in the lungs, whereas Tlr7 and Irf7-deficient mice show increased COVID-19 severity caused by deficient IFN-I and -III activation." (PMID 41445728, 2025).
COVID-19 (continued). "In addition, we found that some TFs were differentially expressed in severe COVID-19, including TF upregulations of IRF7, SP100, HMGB2, and BCL6, and downregulations of FOS and JUNB." (PMID 38612651, 2024). "Our analysis indicated that the common DEGs of COVID-19 and AD are enriched in the pathway of apoptosis, suggesting that apoptosis might be involved in COVID-19 and AD pathophysiology, and IRF7 might play a critical role in apoptosis." (PMID 38257800, 2024). "The best predictive models for mortality comprised IFNB1 or age, viral ORF7a and ACE2 receptor transcripts, whereas comparison with pre-vaccine fatal COVID-19 signatures uncovered a unique IRF3 low/IRF7 high immune signature in post-vaccine fatal COVID-19 outbreaks." (PMID 37217661, 2023). "Despite none of these variants being previously reported for COVID-19 association, IRF7 gene codes for protein necessary to produce IFN-I." (PMID 37795240, 2023). "All signaling molecules of the IFN-I downstream pathway and IRFs (i.e., JAK-1, TYK-2, STAT-1, STAT-2, IRF-3, and IRF-7) showed very reduced expression levels in COVID-19 patients with the severe condition compared to healthy individuals at both RNA and protein levels." (PMID 35842705, 2022). "Studies have shown that the expression level of IRF7 is increased in patients with mild/moderate COVID-19, while those with reduced IRF7 expression due to hypermethylation of the IRF7 promoter gene are likely to develop severe infection after SARS-CoV-2 infection." (PMID 36212830, 2022). "For example, the gene IRF7, a master regulator of the type I IFN response whose loss-of-function associates with life-threatening COVID-19 in human subjects, exhibited increased expression in blood as early as day 1 post-infection and normalized by 14 days post-infection." (PMID 34691074, 2021). "Two functionally similar but mechanistically independent mechanisms related to the type I IFN response, i.e. neutralizing autoantibodies against type I IFNs and inborn errors of TLR3- and IRF7-dependent type I IFN immunity, have been demonstrated to be associated with severe COVID-19." (PMID 34531865, 2021). "In the context of exhaustive inflammation, we observed that TRAM-mediated STAT1/IRF7 circuitry may be involved in the expansion of Ly6C++ monocytes with elevated induction of S100a8, a key signature gene elevated in septic patients including COVID-19 patients." (PMID 35091696, 2022). "The identification of IFIT1, IFITM1, IRF7, ISG15, MX1, and OAS2 as pivotal components suggested their viability as potential drug targets for COVID-19." (PMID 40552037, 2025). "This was characterized by low levels of IRF7, IFNβ1, ISG15 and IFNγ, highlighting the importance of intact TLR7 signaling in the pathogenesis of severe COVID-19." (PMID 41011507, 2025). "To further interrogate type I IFN signaling in critical COVID-19 patients, we quantified protein expression of interferon-stimulated genes (ISGs) MX1, IRF7, and IFIT1 by flow cytometry." (PMID 38231281, 2024). "Comparison with published pre-vaccine fatal COVID-19 transcriptomic and genomic signatures uncovered a unique IRF3 low/IRF7 high immune signature in post-vaccine fatal COVID-19 outbreaks." (PMID 37217661, 2023). "Interferon Regulatory Factor 7 (IRF7), which plays an essential role in innate immunity, is less methylated at particular CpG sites of COVID-19 patients than the normal individual." (PMID 36906872, 2023). "Compared to healthy skin, COVID-19 explants exhibited significant expression of ISGs (IFI35, IRF7 and MX1), and this response was strongly reduced by H-151." (PMID 35045565, 2022). "In this sense, IFN polymorphisms or polymorphisms of the molecules in charge of signaling for their production, such as IRF3, IRF7, TICAM1, TBK1, and STAT2, have also been related to poor prognosis of COVID-19 patients." (PMID 35062298, 2022).
COVID-19 (continued). "Inborn errors of type I IFN immunity with loss-of-function, involving human loci known to govern TLR3 and interferon regulatory factor 7 (IRF7), were found in life-threatening COVID-19 patients." (PMID 34718937, 2022). "Independent prognosis and survival analysis revealed important differential genes, including RACGAP1, TCF7L2, IRF7, DMD, and JUN, which can be used as effective biomarkers for screening and characterizing patients with BRCA and COVID-19 at all stages." (PMID 36060002, 2022). "Activated Myc represses IRF7 which regulates type I IFN production, and correspondingly a significant lower IRF7 expression and a lower IFN response was detected in patients with COVID-19." (PMID 35663963, 2022). "On the other hand, the IRF7 (Interferon regulatory factor 7) and IFNG (Interferon Gamma) were found to be downregulated in severe COVID-19 patients." (PMID 35422859, 2022). "They revealed how inborn errors at the 13 human loci, which are known to govern TLR3- and IRF7-dependent type I IFN immunity, can lead to life-threatening pneumonia in COVID-19 patients." (PMID 34976886, 2021). "Our findings illustrating increased IRF7 and IRF3 mRNA levels in COVID-19 patients with mild/moderate disease further confirm their role in the host antiviral response." (PMID 33780352, 2021). "In our study, we report that IRF7, ISG15, IFI44L, IFIT1, and IFIT3 gene expression is increased in CD16+ monocytes from people with mild COVID-19 compared to healthy controls." (PMID 34108966, 2021). "IRF7 (interferon regulatory factor 7) can mediate inflammatory responses, and a lack of IRF9 results in increased COVID-19 risk." (PMID 40877796, 2025). "ISGs, such as IFIT and IFITM, ISG15, IFIH1, MX1, IRF7, OAS 1-3, and STAT1 are recognized for enhancing IFN signaling, thereby contributing to antiviral activity, emerge as potential candidates for drug targets in COVID-19 treatment." (PMID 40552037, 2025). "In another independent study focusing on the methylomes of peripheral blood samples from COVID-19 patients after a 3-month recovery, we found that the DNA methylation status of IRF7 has not been completely restored." (PMID 38257800, 2024). "IRF7 is strongly hypomethylated in SARS-CoV-2 individuals, and IRF7 DNA methylation signatures may differentiate patients with SARS-CoV-2 infection from uninfected individuals and predict COVID-19 disease severity." (PMID 37638030, 2023). "We focus on the latest regulatory mechanisms of IRF7 in IFN-I, including signaling pathways, transcription, translation, and post-translational levels, the dimerization and nuclear translocation, and the role of IRF7 in IFN-III and COVID-19." (PMID 37638030, 2023). "Most striking was the under-expression of genes involved in viral recognition (e.g. TLR7, UNC93B, RIG-I/DDX58), as well as genes encoding downstream signaling molecules and transcription factors (e.g. TRIF/TICAM1, MYD88, IRF7), with the notable exception of IRF4, in COVID-19 compared to INFL." (PMID 34135895, 2021). "Furthermore, the downstream factors of TLR7 and BTK in TLR pathway, such as MYD88, IRF7, NFKB1, and JUN, and cytokines (TNF, IL1B, and IL18) were elevated in men with severe COVID-19." (PMID 34330889, 2021). "The limited change in IRF7 could reflect the relatively mild cases of COVID-19 in this study, which would not require prolonged IFN production." (PMID 39000027, 2024). "In comparison to the COVID-19(-) PU controls, genes highly expressed in the TV group fell into categories that included neutrophil dysfunction (CD274, PADI2), inhibition of B and T cell responses (CD22, IRF4, ORAI1), and upregulation of pro-inflammatory response pathways (CARD8, MAPK7, IRF7, IFIH1)." (PMID 37026002, 2023). "Moreover, it was found that increasing IFIT1 and IFIT3 has been reported previously in CD16+ monocytes of mild and severe COVID-19 patients, while the IRF7 was not differentially expressed." (PMID 35422859, 2022).
COVID-19 (continued). "Thus, the upregulation of IRF2, IRF7, and STAT, in all cell types may be driving the amplification of IFN response pathways and thereby the overproduction of inflammatory cytokines that contribute to COVID-19 CRS pathogenesis." (PMID 34163359, 2021). "However, by using COVID-19 cohort samples, we demonstrated that non-heat-inactivated serum from mild and severe COVID-19 patients similarly suppressed IFNβ, ISG IRF7, and cytokine IL-6 induced by complement-opsonized SARS-CoV-2." (PMID 38418557, 2024).